TNF (tumor necrosis factor)
Diseases named in the same sentence as TNF in open-access papers (continued):
Sharing a sentence is not in itself a finding about the gene and the disease.
musculoskeletal disorders (19 papers, 2010 to 2025). "Tumor necrosis factor (TNF) is a powerful pro-inflammatory cytokine and immuno-regulatory molecule, and modulates susceptibility to musculoskeletal diseases." (PMID 24069456, 2013). "Previous replicated studies have implicated the TNF locus rs361525 in susceptibility and severity of many musculoskeletal diseases." (PMID 24069456, 2013). "Specifically, EA can modulate the release of pro-inflammatory cytokines such as IL-6, TNF-α, and IL-1β, which are key mediators of the inflammatory response in musculoskeletal disorders." (PMID 41567770, 2025). "It has earlier been shown that musculoskeletal disorders due to overuse in humans lead to elevated levels of inflammatory biomarkers, including TNF-alpha." (PMID 29183282, 2017). "For example, serum levels of TNF-α, IL-1β and IL-6 correlate positively with presence of musculoskeletal disorders symptoms in patients, and TNF-α levels are even predictive of symptom severity." (PMID 24015193, 2013). "TNF plays an important role in the pathogenesis of musculoskeletal disease, and its blockade has become a major therapeutic tool in their treatment." (PMID 24069456, 2013). "There was a higher proportion of deaths in the anti-TNF group than in the comparison group resulting from diseases of the musculoskeletal system (15% versus 5%), primarily RA." (PMID 20662063, 2010). "Concerning the interaction with seed genes, we confirmed that interleukin/protein kinase/TNF-alpha inhibitors, drugs for musculoskeletal system disorders, TUDCA, immunosuppressants, antirheumatic agents, and simvastatin and atorvastatin were among the potential drug classes, regardless of PBC stage." (PMID 35884999, 2022). "Despite the considerable published literature, the contribution of these regulatory elements to TNF activation and expression is incompletely understood, and the functional relevance of rs361525 on TNF promoter activity in the setting of musculoskeletal disease remains unclear." (PMID 24069456, 2013). "In a human study, elevated inflammation associated chemotactic cytokines, such as IL-1β, IL-6, CRP and tumor necrosis factor-α (TNF-α), were suggested to be contributors to musculoskeletal disorders." (PMID 26833397, 2016). "RCTs and clinical trials revealed, after BT, a reduction in circulating levels of pro-inflammatory molecules, such as TNF-α, IL-1β, and C-reactive protein, and an increase in anti-inflammatory molecules such as the IGF-1 growth factor especially in musculoskeletal diseases." (PMID 34035862, 2021). "Serum TNF-α, IL-6, TGFB1, CTGF and MMP2 may serve as serum biomarkers of work-related musculoskeletal disorders, although further studies in humans are needed." (PMID 24015193, 2013).
central nervous system diseases (14 papers, 2010 to 2025). "Similarly, pro-inflammatory cytokine TNF-α is related to agitation severity in AD and IL-1β is implicated in contributing to disease severity in various central nervous system diseases including AD." (PMID 37679689, 2023). "It is involved in astrocyte activation, generation of pro-inflammatory factors IL-6, IL-1β, and TNF-α, and macrophage and T-cell infiltration, thus leading to secondary inflammatory injury in central nervous system diseases." (PMID 31681297, 2019). "We augment this previously unarticulated concept of a unifying pathophysiology of central nervous system disease, with reports of benefits of TNF alpha inhibition in many hundreds of patients with those diseases, including AD." (PMID 26664821, 2015). "Whether TNF-Exo could be utilized to affect other central nervous system diseases is an interesting question needed to be answered." (PMID 40027193, 2025). "The top five predicted drugs that might upregulate MEG3 include RN-1734, a TRPV4 antagonist that was shown to reduce demyelination in central nervous system diseases as well as inhibit glial activation and IL-β and TNF-α production." (PMID 36869839, 2023). "Together, these experiments suggested that sCABs efficiently suppressed TNF‐α in the PD mouse brain and significantly ameliorated the symptoms of PD, suggesting that sABs have the potential to be a brain‐targeting delivery carrier for the treatment of central nervous system diseases such as PD." (PMID 34258157, 2021).
neurodevelopmental disorder (12 papers, 2010 to 2026). A behavioral and cognitive disorder with onset during the developmental period that involves impaired or aberrant development of intellectual, motor, or social functions. "MADD interacts with tumor necrosis factor alpha in activating the mitogen‐activated protein kinase pathway and has been associated with neurodevelopmental disorders." (PMID 40665476, 2025). "While we show that elevated TNF-α alone is sufficient to induce some neurodevelopmental abnormalities, we believe that it is unlikely that elevated cytokines by themselves will be the sole cause of neurodevelopmental disorders." (PMID 20067608, 2010). "Elevated levels of inflammatory cytokines such as IL-6, IL-1β, and TNF-α in blood and cerebrospinal fluid have been reported in patients with neurodevelopmental disorders." (PMID 41465426, 2025). "TNF-α levels tend to be elevated in neurodevelopmental disorders, indicating an inflammatory response in the CNS." (PMID 39329976, 2024). "In this study, we focused on a set of three pro-inflammatory cytokines - IL-1β, IL-6 and TNF-α - that are known to be elevated in neurodevelopmental disorders and have known effects on neuronal function." (PMID 20067608, 2010). "Researchers have observed that in neurodevelopmental disorders such as ASD, TNF-α increases in parallel with certain interleukins." (PMID 39329976, 2024). "The selected cytokines comprised IL-1β, IL-6, IL-10, TNF-α, and IFN-γ, which have not only been found dysregulated in the MIA paradigm, but also form part of the inflammatory profiles in the neurodevelopmental disorders reflected in the MIA model (eg)." (PMID 39033141, 2024). "Although we have identified that low‐dose TNF‐α can increase the phosphorylation of NF‐κB and the expression of ALX4, a better understanding of immune responses among mice model of neurodevelopmental disorders is likely to discover more potential drugs." (PMID 33304758, 2020).
skeletal diseases (12 papers, 2016 to 2025). "The association between inflammatory cytokines and bone disorders markers, IL-6, TNF-α, OPN, OPG, and FGF-23, reflects the severity of vascular changes in CKD and predicts disease progression." (PMID 27667892, 2016). "Estrogen deficiency can also increase the concentration of IL-1, TNF-α, and other bone metabolism markers, i.e., bone alkaline phosphatase (bALP) as a marker of bone formation and bone disorders, as well as tartrate-resistant acid phosphatase (TRAP) as a bone resorption marker." (PMID 34065038, 2021). "Of course, this TNF‐based experimental bone defect model needs further confirmation from other animal models to strengthen its relevance for human bone disorders." (PMID 40913251, 2025). "Given the inflammatory background of bone disorders, this study aimed to assess the impact of TNF-α gene expression and its serum level on bone mineral density (BMD) in individuals with CD." (PMID 41141340, 2025). "TNF-α (also known as cachectin) has been identified as a pro-inflammatory cytokine that plays a role in many skeletal diseases." (PMID 29321835, 2017). "Out of all analyzed candidate biomarkers, a panel which includes mediators of inflammation (IL-6, TNF-α) and mineral and bone disorder biomarkers (OPG, OPN, OCN, FGF-23, and Fetuin-A) was found to be more relevant than a single biomarker to detect patients in early CKD stages." (PMID 27667892, 2016). "A panel of proteomic biomarkers, assessed by xMAP array, which includes mediators of inflammation (IL-6, TNF-α) and mineral and bone disorder biomarkers (OPG, OPN, OCN, FGF-23, and Fetuin-A), was found to be more relevant than a single biomarker to detect early CKD stages." (PMID 27667892, 2016). "Additionally, TNF-α acts as an inflammatory cytokine in several skeletal diseases." (PMID 30889841, 2019). "However, the application of IFN-γ plus TNF-α preconditioned MSCs in bone disorders could be limited by the potential detrimental effect of IFN-γ plus TNF-α on MSC self-renewal and lineage differentiation." (PMID 29212557, 2017).
heart (11 papers, 2005 to 2025). "Adenosine deaminase levels, IL-10 receptor subunit beta levels, TNF-related apoptosis-inducing ligand levels, and TNF-related activation-induced cytokine levels exhibited a causal relationship with thymic benign tumors and were risk factors." (PMID 38828408, 2024). "Adenosine deaminase levels, interleukin-10 receptor subunit beta expression, tumor necrosis factor (TNF)-related apoptosis-inducing ligand levels, and TNF-related activation-induced cytokine levels showed a causal relationship with thymic benign tumors, which are its risk factors." (PMID 38828408, 2024). "The aim of the present study was to determine whether differences exist in immunohistochemical staining of cytokines, TNF-α and interleukin-10 (IL-10) between benign tumors and malignant primary ovarian tumors." (PMID 25624918, 2015). "The deleterious effects of TNF-α on fibroblasts may aggravate heart inflammation mediated through the up-regulation of adhesion molecules such as vascular cell adhesion molecule-1 (VCAM-1)." (PMID 26173590, 2015). "Benign tumors were recorded seven times during TNF-α-blocking therapy." (PMID 15899052, 2005). "Previous studies have indicated that LD has antiinflammation effect and that the inflammatory response participates in I/R-induced cardiac injury; thus the effects of LD on inflammatory cytokines (IL-6, TNF-α and CRP) were also detected in the ischemic heart." (PMID 26058040, 2015). "Thus, plasma mediators released in the circulation 4 h after open heart surgery strongly suppressed LPS-induced TNF-α but not IL-6 synthesis by monocytes." (PMID 22506067, 2012).
genetic disease (9 papers, 2009 to 2025). "Humans suffering from this genetic disease exhibit severe skin inflammation, paradoxically due to impaired NF-κB activation and reduced resistance to TNFα/TNFR1-mediated apoptosis." (PMID 24802997, 2014). "When comparing the top 20 ADRs reported for each anti-TNFα drug in the SOCs, all the five TNFα inhibitors had different PTs of ADR in congenital, familial, and genetic disorders." (PMID 37554981, 2023). "We found that the five TNFα inhibitors had different PTs of ADR in congenital, familial, and genetic disorders." (PMID 37554981, 2023).
endocrine disorders (8 papers, 2012 to 2025). "Thirteen studies reported the impact of different type of probiotics on TNF-α in human or animals with endocrine disorders." (PMID 38504163, 2024). "Circulating inflammatory mediators, such as interleukin (IL) -1β, IL-6 and tumor necrosis factor (TNFα), play an important role in the induction of endocrine disorders during inflammation." (PMID 32967383, 2020). "Based on our findings it seems to be reasonable that a therapy focused on inhibiting TNFα synthesis could have some beneficial effect on the endocrine disorders which commonly accompany prolonged inflammatory states, such as reproduction disorders." (PMID 32967383, 2020). "It seems that regulating the immune system and suppressing pro-inflammatory pathways like tumor necrosis factor-α and interleukin-6 or triggering anti-inflammatory pathways like interleukin-4 and 10 may be one of the potential mechanisms in the managing of endocrine disorders." (PMID 38504163, 2024).
hematologic cancers (7 papers, 2014 to 2025). "This study has investigated the consequences of promoter SNPs in apoptosis genes Bax-248G>A (rs4645878)/Bcl-2-938C>A (rs2279115) and pro-inflammatory cytokines TNF-α rs1800629 G>A/IL-8 rs4073 T>A on the risk and susceptibility towards hematological cancers." (PMID 37232720, 2023). "Several inflammatory cytokines, including tumor necrosis factor-α (TNF-α), interferon-γ, interleukin (IL)-6, and IL-8, play a role in the pathogenesis of both immune-mediated diseases and hematologic cancers." (PMID 29287101, 2017).
movement disorder (6 papers, 2022 to 2025). Neurological conditions resulting in abnormal voluntary or involuntary movement, which may impact the speed, fluency, quality and ease of movement. "ACR caused movement disorders, triggered oxidative stress, and raised TNF-α, IL-1β, and caspase-3 cleaved levels." (PMID 38333747, 2024). "In summary, there appears to be an increase in proinflammatory cytokines most clearly for TNF-α, but probably also for IL-17 and IL-1β, in children with obsessive-compulsive and movement disorder symptoms compared to healthy controls." (PMID 36061386, 2022). "Compared to the ACR-treated rats, administration of vitamin E reduced movement disorders, decreased MDA levels, increased GSH content, and lowered levels of TNF-α, IL-1β, and cleaved caspase-3 in rat cortical tissue." (PMID 40292259, 2025). "The present results indicate that the injection of ACR (50 mg/kg) for 11 days significantly led to movement disorders, decreased GSH content, and increased amounts of MDA, TNF-α, IL-1β, and caspase-3, resulting in the induction of oxidative stress, inflammation, and apoptosis in the brain cortex." (PMID 38333747, 2024). "In this study, vitamin E was employed as a positive control, supplementing vitamin E with ACR reduced movement disorders, reduced MDA, increased GSH content, and significantly reduced TNF-α, and caspase-3 levels in cortex tissue compared to the ACR receiving group." (PMID 38333747, 2024).
animal disease (3 papers, 2019 to 2023). "Similar effects are seen in mice administered systemically with TNFα, leading to the use of TNFα-injected mice as an animal disease model for the study of cell death and cytokine responses." (PMID 37828052, 2023).
gynecologic tumor (2 papers, 2008 to 2022). "Previously, an increase in cell lysis has been observed after the treatment of gynecologic tumor cell lines with interferon-γ and TNF-α." (PMID 18257926, 2008). "A similar antiproliferative synergism has also been observed when treating gynecologic tumor cell lines with delta 12-prostaglandin J2 and TNF." (PMID 18257926, 2008).
reproductive diseases (2 papers, 2015 to 2019). "TNF-α is not only a key regulator in interactions prior to the implantation, but also higher levels of it plays a crucial role in some reproductive diseases such as endometrial infections and recurrent spontaneous abortions." (PMID 26568760, 2015). "Hence, it seems that exercise could be a promising target to modulate TNF-α concentrations at the maternal-fetal interface during pregnancy, which might help to prevent immunometabolic dysregulations and reproductive diseases." (PMID 31684183, 2019).
skeletal muscle disorder (2 papers, 2012 to 2025). A disease involving the skeletal muscle tissue. "On the other hand, if TNF-α inhibitors may cause an increase in body weight by impairing lipolysis, blocking TNF-α signaling could become a new strategy to treat skeletal muscle disorders with severely reduced weight loss, such as cancer cachexia." (PMID 41141350, 2025).
endocrine neoplasms (1 paper, 2025). "Of all the biomarkers analyzed in our study, significant differences in TNF-α serum concentrations were observed between patients with endocrine neoplasms and healthy control groups." (PMID 40507492, 2025). "The significant increase of TNF-α serum concertation in patients with NET and MTC compared to the control group (p = 0.004 and p = 0.005, respectively) underscores its potential as a biomarker for these endocrine neoplasms." (PMID 40507492, 2025).
genodermatosis (1 paper, 2024). "This may encourage future research efforts to understand the role of TNF-α in HHD, as well as to develop randomized trials to assess the efficacy of adalimumab in this genodermatosis." (PMID 39295647, 2024).
head and neck tumor (1 paper, 2024). "In some preclinical studies, chemokines, cytokines, and other factors including lymphotoxin α (LTα), tumor necrosis factor-α and interleukin-2 were found that could induce the formation of TLS in head and neck tumor-bearing mice." (PMID 38583352, 2024).
hepatobiliary disorder (1 paper, 2026). A non-neoplastic or neoplastic disorder that affects the liver, bile ducts, and gallbladder. "Overall, adalimumab showed the most robust and consistent association with hepatobiliary disorders across both pharmacovigilance databases, while findings for the other TNF-α inhibitors were negative or inconclusive." (PMID 41601665, 2026).
neuromuscular disease (1 paper, 2022). "Increasing plasma creatinine and TNF‐α in HTLV1‐infected mice may be associated with the initiation of inflammatory reactions and the induction of neuromuscular disease or cardiovascular system injury." (PMID 35373925, 2022).
osteoarthropathy (1 paper, 2015). "In the acute stage of the osteoarthropathy, serum concentrations of TNF-α are raised." (PMID 26137498, 2015).
TNF also shares sentences with these, for which no sentence is quoted: chronic periodontitis (125 papers); multiple myeloma (84); acute myocardial infarction (62); American trypanosomiasis (28); viral diseases (26); portal hypertension (16); magnesium deficiency (15); cardiac arrhythmias (13); leukoplakia (13); hypertrophy (12); Ventricular hypertrophy (11); acute respiratory failure (9); chronic prostatitis (8); acute myocarditis (6); autonomic dysfunction (6); glomerulopathies (6); Hearing impairment (6); hematologic neoplasms (6); hepatorenal syndrome (6); immune thrombocytopenia (6); metastasis (6); migraine with aura (6); thrombophilia (6); adult respiratory distress syndrome (5); B-cell acute lymphoblastic leukemia (5); chronic infantile neurological cutaneous articular syndrome (5); complex regional pain syndrome (5); concussion (5); Hematochezia (5); idiopathic dilated cardiomyopathy (5).
A further 476 diseases each share a sentence with TNF in 5 papers or fewer.